H3C2 (H3 clustered histone 2)
Description:
Core component of nucleosome. Nucleosomes wrap and compact DNA into chromatin, limiting DNA accessibility to the cellular machineries which require DNA as a template. Histones thereby play a central role in transcription regulation, DNA repair, DNA replication and chromosomal stability. DNA accessibility is regulated via a complex set of post-translational modifications of histones, also called histone code, and nucleosome remodeling.
Synonyms: H3FL; HIST1H3B; H3/l
Gene: Protein-coding gene on chromosome 6 (26,031,589 to 26,032,099, reverse strand). Ensembl gene ENSG00000286522.
Subcellular location: Nucleus; Chromosome
Subcellular location (Human Protein Atlas): Nucleoplasm
Pathways (Reactome):
Gene expression (Transcription): B-WICH complex positively regulates rRNA expression; DNA methylation; ERCC6 (CSB) and EHMT2 (G9a) positively regulate rRNA expression; MLL4 and MLL3 complexes regulate expression of PPARG target genes in adipogenesis and hepatic steatosis; NoRC negatively regulates rRNA expression; PRC2 methylates histones and DNA; RNA Polymerase I Promoter Escape; RNA Polymerase I Promoter Opening; RUNX1 regulates genes involved in megakaryocyte differentiation and platelet function; RUNX1 regulates transcription of genes involved in differentiation of HSCs; Regulation of endogenous retroelements by KRAB-ZFP proteins; Regulation of endogenous retroelements by Piwi-interacting RNAs (piRNAs); Regulation of endogenous retroelements by the Human Silencing Hub (HUSH) complex; SIRT1 negatively regulates rRNA expression; Transcriptional regulation by small RNAs
Chromatin organization: CHD1 and CHD2 subfamily; CHD6, CHD7, CHD8, CHD9 subfamily; ChAHP complex assembly; Chromatin modifying enzymes; HATs acetylate histones; HDACs deacetylate histones; HDMs demethylate histones; Interaction of NuRD complexes with transcription factors; NuRD complex assembly; PKMTs methylate histone lysines; RMTs methylate histone arginines
Disease: Defective pyroptosis; Dengue Virus-Host Interactions; HCMV Early Events; HCMV Late Events
Signal Transduction: Activated PKN1 stimulates transcription of AR (androgen receptor) regulated genes KLK2 and KLK3; Estrogen-dependent gene expression; Formation of the beta-catenin:TCF transactivating complex; Pre-NOTCH Transcription and Translation
Developmental Biology: Activation of anterior HOX genes in hindbrain development during early embryogenesis; Chromatin modifications during the maternal to zygotic transition (MZT); Transcriptional regulation of granulopoiesis
Immune System: FXIIa activates plasma kallikrein-kinin system; Interleukin-7 signaling; Regulation of PD-L1(CD274) transcription
and 8 more pathways
Gene Ontology:
Molecular function: cadherin binding; protein binding; structural constituent of chromatin; nucleosomal DNA binding; DNA binding; protein heterodimerization activity
Biological process: epigenetic regulation of gene expression; nucleosome assembly; chromatin organization; heterochromatin formation; telomere organization
Cellular component: chromatin; extracellular exosome; membrane; nucleoplasm; nucleosome; nucleus; protein-containing complex; extracellular region; chromosome
Genetic constraint (gnomAD): Loss-of-function variants: 13 observed, 9.52 expected, observed/expected ratio (o/e) 1.37, 90% interval 0.87 to 1.89. That is too few expected variants to judge how well the gene tolerates losing a copy. Missense variants: 144 observed, 203.46 expected, observed/expected ratio (o/e) 0.71, 90% interval 0.62 to 0.81. Synonymous variants: 166 observed, 84.01 expected, observed/expected ratio (o/e) 1.98, 90% interval 1.7 to 1.99.
Homologues: Orthologues: Drosophila melanogaster His3:CG33812 (99% identical), zebrafish si:ch1073-153i20.2 (99% identical), zebrafish si:ch211-113a14.20 (99% identical), zebrafish si:ch211-113a14.23 (99% identical), zebrafish si:ch211-113a14.27 (99% identical), zebrafish zgc:173552 (99% identical), Caenorhabditis elegans his-17 (97% identical), Caenorhabditis elegans his-2 (97% identical), Caenorhabditis elegans his-32 (97% identical), Caenorhabditis elegans his-40 (97% identical), Caenorhabditis elegans his-42 (97% identical), Caenorhabditis elegans his-45 (97% identical), and 5 more. Paralogues in human: H3C1 (100% identical), H3C10 (100% identical), H3C11 (100% identical), H3C12 (100% identical), H3C3 (100% identical), H3C4 (100% identical), H3C6 (100% identical), H3C7 (100% identical), H3C8 (100% identical), H3C13 (99% identical), H3C14 (99% identical), H3C15 (99% identical), and 8 more.
Diseases named in the same sentence as H3C2 in open-access papers:
H3C2 is named in the same sentence as 14 diseases in open-access papers, as found by Europe PMC text mining. Sharing a sentence is not in itself a finding about the gene and the disease. The quoted sentences say what the papers report.
Alzheimer disease (1 paper, 2021). A progressive, neurodegenerative disease characterized by loss of function and death of nerve cells in several areas of the brain leading to loss of cognitive function such as memory and language. "For example, H3C2 plays an essential role in brain development in early embryonic development, and H2BC12 is involved in Alzheimer's disease." (PMID 34660567, 2021).
tumor (1 paper, 2024). "Spatial transcriptome analysis revealed notable upregulation of EZH2 and the histone family gene such as H3C2 (H3‐clustered histone 2) in SNUC tumor cells." (PMID 39565059, 2024). "Among the genes identified as significantly upregulated or downregulated in SNUC, EZH2 and the histone family gene, such as H3C2 (H3 clustered histone 2), were notably upregulated in SNUC tumor cells (fold change > 1.5 times, p < 0.05)." (PMID 39565059, 2024).
H3C2 also shares sentences with these, for which no sentence is quoted: infection (2 papers); viral infection (2); ADNP syndrome (1); cancer (1); cardiac hypertrophy (1); gastric cancer (1); glioblastoma (1); glioma (1); hypertrophy (1); hypophysis (1); pneumonia (1); smallpox (1).